MPO (myeloperoxidase)
Diseases named in the same sentence as MPO in open-access papers (continued):
Sharing a sentence is not in itself a finding about the gene and the disease.
tumor (425 papers, 1958 to 2026). "N1+ neutrophils were defined as tumour-associated N1 neutrophils that release NETs, specifically MPO+CD11b+CD206-citH3+ cells." (PMID 41573639, 2025). "We then sought to validate the association of MPO with tumor aggressiveness suggested by glycoproteomics." (PMID 40430030, 2025). "The S100A8/A9-positive cells identified in the stroma of PCP and the MPO-positive cells observed in both parenchyma and stroma were likely tumor-associated neutrophils." (PMID 40721446, 2025). "N2+ neutrophils were defined as tumour-associated N2 neutrophils that release NETs, specifically MPO+CD11b+CD206+citH3+ cells." (PMID 41573639, 2025). "PMN-MDSCs can suppress the antigen-presenting capacity of DCs by upregulating myeloperoxidase (MPO) expression, therefore limiting the ability of DCs to cross-present tumor-associated antigens (TAAs)." (PMID 41208963, 2025). "Enhanced MPO activity has been linked to the early stages of lung and breast carcinogenesis and has also been implicated in promoting tumour metastasis." (PMID 41303900, 2025). "The presence of NET markers such as citrullinated histone H3 (H3Cit), neutrophil elastase (NE) and myeloperoxidase (MPO) has been associated with higher tumor burden and poorer clinical outcomes." (PMID 40801632, 2025). "Tumor-associated neutrophils (TANs) are subdivided into anti-tumor (N1 TANs), by kill tumor cells via myeloperoxidase or histones, or pro-tumor (N2 TANs), enhancing proliferation through protease." (PMID 41583321, 2025). "Combination treatment with verdiperstat and ICT significantly delayed tumor growth compared to ICT alone to levels equivalent to host MPO gene deficiency." (PMID 38367056, 2024). "Loss of myeloperoxidase in isolated myeloid cell subsets from tumor-bearing mice resulted in decreased reactive oxygen species production and T cell suppression." (PMID 38367056, 2024). "Myeloperoxidase (MPO) is a neutrophil-derived enzyme that has been recently associated with tumour development." (PMID 37627581, 2023). "For example, tumor cell ferroptosis, induced by neutrophils via the transfer of granules containing myeloperoxidase, is associated with greater tumor necrosis and poor patient outcomes." (PMID 36768342, 2023). "Rather, we revealed a tendency towards better outcomes in DOX-treated Mpo−/− versus WT mice, which is in line with previous work showing that MPO deficiency limits tumour growth." (PMID 37656254, 2023). "Previous studies in our laboratory have shown that MPO-deficient mice (MPO KO; C57BL/6 MPO−/−) have up to a 40% reduction in tumour size compared to MPO wild-type mice (C57BL/6 MPO+/+)." (PMID 37627581, 2023). "Consistently, in MDSCs depleted or myeloperoxidase (MPO, a key enzyme for the production of oxidized lipids in MDSCs) deficient mice, DCs showed improved activity for tumor antigens cross-presentation." (PMID 37441069, 2023). "Tumor infiltration by MPO+ neutrophils has been associated with a favorable prognosis in colorectal and breast cancers." (PMID 34637051, 2022). "The typical cell markers of tumor‐associated N1 neutrophils were MPO+CD11b+CD206−, and those of tumor‐associated N2 neutrophils were MPO+CD11b+CD206+ by three‐color immunofluorescence (IF) staining." (PMID 36349143, 2022). "It shows the tumor's greenish tint caused by the presence and oxidation of the enzyme myeloperoxidase." (PMID 35036234, 2022). "Further immunostaining revealed many CD163‐positive tumor‐associated macrophages (TAMs), CD15, myeloperoxidase (MPO)‐positive tumor‐associated neutrophils (TANs), and CD3, CD25‐positive regulatory T cells (Tregs) in the tumor." (PMID 33174378, 2021). "The hallmark of tumor inflammation is the infiltration of neutrophils which in turn secret specific tumoricidal enzymes MPO." (PMID 32541769, 2020). "Genetic reduction in MPO levels using the transposon mutant alleles Pxtf05258 and PxtEY03052 decreased tumour incidence." (PMID 31992650, 2020).
tumor (continued). "Thereinto, MPO and lysozyme are specific markers of oral primary GS and are associated with the process of tumor cell differentiation." (PMID 33120806, 2020). "This was replicated by pharmacological blockade of MPO activity by MPO inhibitor-1 treatment, which caused equivalent decreases in tumour incidence." (PMID 31992650, 2020). "An interesting phenomenon is that PDS reduced the neutrophil-lymphocyte ratio (NLR) via its inhibition effect on the granule-monocyte differentiation of spleen cells, which is associated with a decrease in the secretion of tumor MPO, G-CSF, PU.1, and C/EBPα." (PMID 32015754, 2020). "HQD-1 treatment also significantly decreased MPO levels caused by AOM/DSS-treatment in tumor and surrounding tissues." (PMID 27557503, 2016). "Tumor associated neutrophil markers, CD11b, MPO and hARG-1, were detected to validate the differentiation of neutrophils (HL-60N)." (PMID 26079540, 2015). "MPO has been either directly or indirectly linked to neoplasia, which is a well-established risk factor for many types of cancer." (PMID 23991124, 2013). "Recently, Kleijn used a Gadolinium (Gd)-based agent targeting the inflammatory enzyme myeloperoxidase (MPO) in a similar approach to detect oncolytic virus-associated tumor inflammation by MRI." (PMID 23441176, 2013). "Luminol-mediated bioluminescence was used to non-invasively detect myeloperoxidase (MPO) activity which is associated with tumor-infiltrating neutrophils and inflammatory cells." (PMID 21209895, 2010). "Moreover, this review included a thorough analysis of genetic variants, especially in MPO, and the combination of cytokine-mediated pathways with tumor angiogenesis and immune evasion mechanisms." (PMID 41179937, 2025). "Immunofluorescence staining suggested potential co-localization or proximity of MPO-positive neutrophils and cells expressing citrullinated histone H3 (CitH3), a marker often associated with neutrophil extracellular traps (NETs), within the tumor milieu." (PMID 41322418, 2025). "Components of NETs, including histones, MPO, and ROS, have been associated with lipid peroxidation, suggesting that NETs might influence lipid metabolism and thereby impact tumor behavior." (PMID 39849606, 2025). "Tumour-associated N1 neutrophils were defined as MPO+CD11b+CD206- cells, denoted as N1." (PMID 41573639, 2025). "Tumour-associated N2 neutrophils were defined as MPO+CD11b+CD206+ cells and denoted N2." (PMID 41573639, 2025). "While the influence of MPO on T cells and the specific mechanism underlying MPO-dependent cell recruitment requires further studies, our data demonstrate a significant decrease in CD11b+Ly6G+ myeloid cells within the tumor microenvironment when MPO is deficient using multiple methods." (PMID 38367056, 2024). "Using luminol and L-012 bioluminescence imaging, intravital imaging in MPO−/− mice had decreased MPO activity (as expected) and reduced ROS levels within the tumor microenvironment further suggesting that MPO deficiency resulted in a less immunosuppressive microenvironment." (PMID 38367056, 2024). "Since oxidative stressis an important mechanism of cardiotoxicity induced by anti-tumor drugs,myeloperoxidase (MPO) may become an independent risk factor associated withcardiotoxicity, although this hypothesis requires further clinical validation." (PMID 39076949, 2024). "The tumor microenvironment and systemic immune landscape demonstrated significant decreases in myeloid cells, exhausted T cells and T regulatory cell subsets when myeloperoxidase was deficient." (PMID 38367056, 2024). "Furthermore, MPO is involved in the ferroptosis of tumor neutrophils, causing immune suppression of TME in cancer." (PMID 37935721, 2023). "FN1 interacts with MPO, which has controversial role in different diseases, and a type of its gene polymorphism leads to reduced anti-tumour activity that may play a role in development of CC." (PMID 36683048, 2023).
tumor (continued). "In addition, MPO is also implicated in cancer progression, as it affects tumour growth, apoptosis, cell migration, and metastasis." (PMID 37627581, 2023). "In addition to neutrophils, we have previously demonstrated a role for MPO-producing tumor-associated myeloid derived suppressor cells (MDSCs) in MPO production and ultimately in causing homocitrullination within the tumor microenvironment." (PMID 35464453, 2022). "However, it has now been well-established that in fact, MPO-generated ROS and other products such as HOCl potently oxidize and damage DNA, leading to elevated mutational burden and tumor development." (PMID 36293108, 2022). "However, HPD was associated with the density of myeloperoxidase myeloid cells within the tumor and inversely correlated with PD-L1 expression in tumor cells." (PMID 34290608, 2021). "Lo Russo and colleagues found that HPD was associated with tumor-associated macrophages with M2-differentiation and myeloperoxidase (MPO)+ myeloid cells, and that PD-1 inhibition induced FcR triggering of M2-macrophages, promoting aggressive protumorigenic behavior." (PMID 31683809, 2019). "In order to determine whether the tumor-associate neutrophils (TAN) influenced the MPO and ELA activity, which are mediators associated with SCC development, we analyzed for the presence of these enzymes in the tumor microenvironment." (PMID 25268644, 2014). "Importantly, MPO is closely associated with tumor development and may play a role in regulating tumor growth, metastasis, and tumor cell migration." (PMID 40547041, 2025). "More importantly, further in vivo experiments demonstrated that S428‐1145 (25 mg/kg, once daily) significantly inhibited tumour growth and downregulated key NETs biomarkers such as Cit‐H3 and MPO in tumour tissues." (PMID 41496500, 2026). "Immunofluorescence and flow cytometry analyses revealed NF-κB activation in tumor-infiltrating MPO+ neutrophils and a concomitant reduction of CD11b+Gr-1high neutrophils in the BM in OVA-MC38 bearing mice, suggesting therapy-driven myeloid cell egress." (PMID 42162242, 2026). "MPO can contribute to the immune landscape within the tumor microenvironment, so we quantified intratumoral CD8 + cell infiltration." (PMID 40797324, 2025). "NET biomarkers such as citrullinated histone H3 (CitH3), cell-free DNA (cfDNA), and myeloperoxidase–DNA complexes (MPO-DNA) are elevated in HCC patients and correlate with tumor spread, showing diagnostic and prognostic potential." (PMID 41516032, 2025). "Specifically, the role of MPO in tumor immune escape and metastasis, through its modulation of immune cell infiltration and activity, warrants deeper investigation." (PMID 40547041, 2025). "In particular, increased MPO activity within the bone marrow microenvironment facilitates plasma cell homing and tumour expansion." (PMID 41303900, 2025). "For instance, N1 neutrophils can directly kill tumor cells, limit their metastasis, and engage innate immune functions through the secretion of myeloperoxidase (MPO), H2O2, and ROS." (PMID 40387965, 2025). "In terms of neutrophil activation, proportions of MPO+ and arginase 1+ neutrophils were higher in ascites than in tumor, with a 1.4- to 2.6-fold change, respectively." (PMID 41221283, 2025). "As N2-polarized TANs, they suppress CD4+ and CD8+ T cell activity through mechanisms such as myeloperoxidase (MPO) and Fas/FasL expression, while they also release immunosuppressive factors that promote tumor growth, metastasis, and immune evasion." (PMID 40647470, 2025). "And protein components in NETs, such as MPO, histones, and proteases, can exert antitumor effects and kill tumor cells, thus inhibiting tumor growth and progression." (PMID 40979214, 2025). "IAA, on the other hand, is oxidized by myeloperoxidase (MPO) in tumor-infiltrating neutrophils into cytotoxic derivatives in FOLFIRINOX-treated models." (PMID 40771692, 2025).
tumor (continued). "Our findings are consistent with these results, as G31P inhibited CXCL1, CXCL2 and TNF-α in tumor and bleomycin-induced lung tissues, alongside decreased MPO activity and F4/80+ macrophage infiltration." (PMID 41425704, 2025). "Hypochlorous acid and ROS produced by MPO can alter the redox state in the tumor microenvironment, which affects the metabolic pathways of tumor cells, thereby promoting metabolic reprogramming." (PMID 39849606, 2025). "NETs are capable of capturing and confining tumor cells, while they contain antimicrobial proteins and enzymes (e.g. myeloperoxidase MPO and neutrophil elastase NE) that directly kill tumor cells." (PMID 40160822, 2025). "Consistent with neutrophil presence in OSCC, IHC staining confirmed abundant infiltration of MPO-positive neutrophils within human OSCC tumor tissues compared to minimal presence in control tissues." (PMID 41322418, 2025). "Consistent with the proteomic data, MPO showed markedly increased cytoplasmic expression in tumor tissues compared with adjacent normal mucosa, confirming enhanced neutrophil-mediated immune activation." (PMID 41480141, 2025). "Plasma and tumor tissue levels of NETs and MPO–DNA were higher in advanced-stage DLBCL and correlate with inferior survival." (PMID 40076681, 2025). "Conversely, neutrophils also exhibit antitumor properties by releasing neutrophil extracellular traps (NETs), which mediate tumor cell destruction through components such as histones, NE, and myeloperoxidase (MPO)." (PMID 40365348, 2025). "Markers such as chemerin, TSP-1, PON-1, resistin, and MPO correlate with tumour burden and disease activity, while adiponectin and TSP-1 are linked to treatment response." (PMID 41303900, 2025). "Spatial validation confirmed MPO overexpression in tumor-infiltrating immune cells and its correlation with oligomannose content." (PMID 40430030, 2025). "Our findings, together with recent preclinical data, support a model in which MPO contributes to a tumour-permissive niche by promoting oxidative stress, suppressing anti-tumour immunity, and enhancing plasma cell migration." (PMID 41303900, 2025). "We used MPO and Cit-H3 antibodies to label NETs in tumor tissues and classified them into low NETs and high NETs groups based on the proportion of MPO+Cit-H3+ cells." (PMID 41445740, 2025). "TANs were labeled by Ly6G and pro-tumor subsets of TANs were identified by MPO, an established biomarker for tumor-promoting neutrophils." (PMID 39971940, 2025). "N1 TANs directly kill tumor cells by releasing cellular hydrolases and producing ROS and myeloperoxidase (MPO) through degranulation." (PMID 40387965, 2025). "DNase I decreased cfDNA and MPO‐DNA content in the serum and reduced the colocalisation of CitH3 and MPO in tumours." (PMID 39865544, 2025). "They exert antitumour activity through production of reactive oxygen species (ROS), release of proteases (e.g., myeloperoxidase [MPO]), and direct contact-mediated tumour cell killing." (PMID 41451221, 2025). "An extended correlation from a previous study done in our lab showed a strong correlation between basal ROS and NETs in these Gr1+ myeloid cells isolated from subcutaneous KPCY6419 tumor-bearing WT and MPO−/− mice." (PMID 41462673, 2025). "Given the many mechanisms of action of HCQ, we sought to confirm the tumor burden reduction was truly secondary to MPO inhibition." (PMID 40797324, 2025). "MPO inhibition through HCQ resulted in decreased tumor burden and prolonged survival in a murine model of metastatic PDAC." (PMID 40797324, 2025). "In areas with higher neutrophil infiltration, Ly6G, and MPO staining intensities are stronger, likely due to the recruitment of neutrophils in response to local tumor cues." (PMID 39971940, 2025). "Both CD15−MPO+ and CD15+MPO+ cells also correlated with presence of stromal tumor infiltrating lymphocytes (TILs)." (PMID 40652059, 2025).
tumor (continued). "In this system, luminol is oxidated by H2O2 and excess myeloperoxidase (MPO) present in tumor tissue, which subsequently activates Ce6 via Förster resonance energy transfer (RET)." (PMID 40003904, 2025). "Its mechanism is to inhibit NETs formation, reduce neutrophil recruitment and MPO expression in the liver and MDSCs in the lung and tumor by blocking P-selectin, inhibiting NF-κB and STAT3 signalling pathways." (PMID 41019086, 2025). "MPO is foremost presented as a molecule that favours tumour initiation and progression due to the action of MPO-derived oxidants that are able to affect DNA." (PMID 40509281, 2025). "WT mice demonstrated Manders’ overlap coefficients that approached 1, suggesting that MPO-active and ROS producing myeloid cells infiltrated the tumor microenvironment during PDAC progression." (PMID 38367056, 2024). "In an orthotopic xenograft GBM mouse model, inhibition of MPO or depletion of Vps34 reduced necrosis formation, leading to prolonged survival of tumor-bearing mice." (PMID 38806658, 2024). "Using a syngeneic immunocompetent subcutaneous tumor model, ICT efficacy was compared in wild-type C57BL/6 (WT) and age-matched syngeneic MPO-deficient (MPO−/−) animals using the KPCY6419 murine PDAC cell line." (PMID 38367056, 2024). "The systemic immune composition was also evaluated using the spleen of tumor-bearing WT and MPO−/− mice." (PMID 38367056, 2024). "MPO deficiency significantly reduced CD11b+Ly6G+ myeloid cells, macrophages and exhausted CD4+PD1+CTLA4+ T cells within the tumor microenvironment." (PMID 38367056, 2024). "As expected, neutrophils and MDSCs isolated from tumor-bearing WT mice had a statistically significant increase in MPO activity compared to tumor-bearing MPO−/− or healthy (tumor-free) mice quantified using luminol bioluminescence." (PMID 38367056, 2024). "This is evident from MPO−/− mice, which underwent identical tumor cell injections, revealing minimal levels of detectable ROS that did not colocalize with the tumor." (PMID 38367056, 2024). "To test the role of inflammation in FBC tumor formation, we compared sub-cryptal proprial neutrophil infiltration using myeloperoxidase (MPO) as a neutrophil marker for IHC staining." (PMID 36778401, 2024). "When Vps34 expression in LN229TAZ(4SA) cells was silenced by shRNAs, or its activity was inhibited by Vps34-IN1, PKH26+ and MPO+ granules in tumor cells are markedly fewer than controls." (PMID 38806658, 2024). "The normal role of these cells is to eliminate pathogens or tumor cells through the production—during inflammation—of cytokines, proteases, chemokines, reactive oxygen species (ROS), and myeloperoxidase (MPO)." (PMID 39735530, 2024). "Previous studies found that myeloperoxidase (MPO) is involved in promoting tumor cell ferroptosis in vitro." (PMID 38806658, 2024). "Only with ICT treatment, when T cells are activated, are differences in tumor growth detected, highlighting the contribution of MPO in shaping an immunosuppressive microenvironment." (PMID 38367056, 2024). "In 14 patients, both MPO and H3cit levels increased in posttreatment biopsies, suggesting that the combinational treatment of CB-839 and capecitabine led to increased tumor-infiltrating neutrophils and induction of NETs." (PMID 38194275, 2024). "In this process, neutrophil-derived myeloperoxidase (MPO) is transferred to tumor cells and responsible for inducing tumor cell ferroptosis." (PMID 38806658, 2024). "To verify this, we performed immunofluorescence staining on xenograft tumor model tissue sections, using Cit H3 and MPO antibodies, common markers for detecting NET formation." (PMID 38613157, 2024).